PDC (phosducin)
Diseases named in the same sentence as PDC in open-access papers (continued):
Sharing a sentence is not in itself a finding about the gene and the disease.
tumor (continued). "The downregulation of IRF7 pathway as well as other factors of tumor microenvironment such as PGE2 and TGFβ abrogate the ability of pDC to release INFα." (PMID 34588926, 2021). "Taken together, these results demonstrate, for the first time, the critical role of pDC in orchestrating CVA21-induced innate and adaptive anti-tumor immune responses and confirm the immunotherapeutic potential of this agent." (PMID 31262361, 2019). "However, in melanoma, pDC activation by TLR-L could trigger potent anti-tumor effects." (PMID 20454561, 2010). "Notably, five tumour tissue samples with high NQO1 mRNA levels showed NQO1 activation, which was confirmed in the corresponding PDC." (PMID 39707614, 2025). "pDC enables the expression of the cytotoxic molecules granzyme B and TRAIL, induces cDC1 maturation, and enhances the function of CD8+ T cells and NK cells in the TME, hence blocking tumor growth." (PMID 40297580, 2025). "We extracted cells from the myeloid cluster of the tumor fraction; these cells were clustered in 10 myeloid cell types including, monocyte, macrophage-like, dendritic cells (DC) 1, DC2, DC2 C1Q+, DC IL22RA2, pDC, AS-DC, mregDC, and granulocyte." (PMID 38611120, 2024). "Given the observed positive link between GPR27 and pDC presence, it’s plausible that the interaction between GPR27 and pDC might contribute, at least in part, to GPR27′s tumor-fighting properties." (PMID 38638156, 2024). "Here we show, in a human in vitro setting, that only cDC1, but not pDC, cDC2 or moDC can relay CD4+ T-cell help for CTL priming to cell-associated tumor antigens." (PMID 36639382, 2023). "In the case of PDC-treated mice, the size of the tumours was not significantly smaller at the termination of the experiment compared to controls; however, L5 and L6 treatments resulted in 21.4% and 31.4% growth inhibition, respectively." (PMID 36834815, 2023). "Compared to antibodies, PDC such as TH1902 may offer many advantages in terms of intracellular uptake, tumor penetration, conjugation chemistry and manufacturing." (PMID 35454785, 2022). "In total, 38 of 43 tumor organoids and 19 of 23 cell lines from the 12 patients were successfully screened in experimental duplicate, generating >1300 measurements of PDO and PDC‐drug interactions." (PMID 34918496, 2022). "Specially, tumor-infiltrating DC2 cells have been proven to be highly heterogeneous populations and deviated substantially from the other homogeneous cell types including DC1, LAMP3+ DC, and pDC." (PMID 32572028, 2020). "RRAD expression was also examined in patient-matched samples, and all tumor tissue, including PDC from ascites, harbored more RRAD overexpression than non-tumor tissue." (PMID 31857616, 2019). "However, in spite of suggestions that they may be involved in the initiation of the response by producing IFN-α in the tumor microenvironment, their role is still not convincing and, actually, some human studies have even associated pDC infiltration of tumors with poor survival." (PMID 29050360, 2017). "Among these, pDC, NK, and neutrophils did not have significant differences between the two tumor sites and were eliminated from further study." (PMID 28250928, 2017). "Unlike enzyme-responsive peptides, which modify PDC structure upon enzyme interaction, enzyme-sensitive peptide linkers break down completely to liberate the drug, ensuring precise and efficient delivery at the tumor site." (PMID 40428099, 2025). "In fact, tumor-targeted therapy with BRAFi profoundly remodels the myeloid immune compartment in the TME with a transient accumulation of inflammatory monocytes and pDC including the recently described Mono (ACT) subtype resembling moDC by their marker expression." (PMID 38631706, 2024). "Interestingly, pDC, macrophages and endothelial cells were abundant in tumor samples rather than in normal groups." (PMID 38440732, 2024).
tumor (continued). "However, some studies have shown that pDC has negative immunomodulatory properties in the TME and is associated with poor clinical outcomes due to tumor tolerance to tumor suppression." (PMID 38279145, 2024). "Some researchers have reported that GZMB is not involved in pDC-induced tumor cell killing." (PMID 37817484, 2023). "We noticed also that pDC depletion does not affect tumor growth independently of frOpn1." (PMID 35878016, 2022). "In the tumor microenvironment, pDC could not effectively activate T cells to kill tumor cells, but induced the production of various regulatory T cells (Tregs) and promoted the immune escape of tumor cells." (PMID 35126478, 2022). "We found that PDC without the MMP‐2‐sensitive linker (PVGLIG) could not achieve the tumor suppressive activity of SynB3‐PVGLIG‐PTX in the GBM cells." (PMID 33552853, 2021). "Unfortunately, none of these studies clarified whether tumor-infiltrating pDC are effective as a predictor for LN metastasis based on a large clinic sample." (PMID 33854604, 2021). "Therefore, pDC, as a main source of type I IFN, is an attractive target for therapeutic manipulations of the immune system to elicit a powerful immune response against tumor antigens in combination with other therapies." (PMID 19190769, 2008). "Thus, although direct evidence is lacking, pDC-tumor cell crosstalk may vary between HPV positive and negative tumors." (PMID 37817484, 2023). "While pDC depletion alone did not have a big impact on tumor growth, IFNAR1 blockade did have an effect and combination pDC depletion and IFNAR1 blockade had the greatest impact." (PMID 37917174, 2024). "In both radical tumor nephrectomy specimens, CD303+ pDC were easily identified but could not be visualized in similar areas of specimens from normal kidney donors." (PMID 26999595, 2016). "Furthermore, CTL priming assays (performed without the addition of autologous mDC) also revealed the importance of pDC, as the absence of CD14+ did not significantly decrease the production of tumor-specific CTLs; however, removal of pDC significantly reduced levels of tumor-specific CTL." (PMID 31262361, 2019).
infection (86 papers, 2008 to 2025). The state of being infected such as from the introduction of a foreign agent such as serum, vaccine, antigenic substance or organism. "Despite exposing hosts to increased risk of secondary infection, pDC loss of function appears to be conserved across LCMV infection in mice, SIV infection in macaques, and humans infected with HIV82–85, HCV86–89,100, HBV91–93 or SARS-CoV-2101." (PMID 39920132, 2025). "It is thus tempting to assume that infection with the pathogenic strain compromises the pDC function, while the C-strain in associated, bystander cells stimulated the correct pDC function." (PMID 34445493, 2021). "Investigating γδ T cell function in mice deficient for pDCs, and pDC function in mice deficient for γδ T cells in the context of infection or cancer would provide significant relevance for the phenomena that we described in vitro." (PMID 32435249, 2020). "A significantly higher number of C. rodentium were found in mice depleted of pDC from 7 days after infection and pDC depleted mice showed increased gut pathology and higher levels of mRNA encoding inflammatory cytokines in the colon upon infection." (PMID 31024525, 2019). "The unusual time frame during which pDC presence in vivo is required for FL to protect against later infections suggests that the underlying mechanisms are likely complex and challenging to dissect." (PMID 28228109, 2017). "pDC loss from the circulation was associated with active caspase-3, suggesting pDC apoptosis during primary infection." (PMID 28572564, 2017). "It is clear from the pDC data that infection causes a different level of activation that is distinct from just binding of surface receptors." (PMID 21297989, 2011). "Importantly, our study is the first to investigate how pDC metabolism changes in vivo following infection, and how these metabolic adaptations relate to pDC loss of function." (PMID 39920132, 2025). "Interestingly and quite contrary, productive infection by the gammaherpesvirus Kaposi’s sarcoma-associated virus (KSHV) is required for pDC activation." (PMID 34843605, 2021). "pDC-depleted mice suffered severe weight loss and morbidity during the course of infection, however we suggest the weight loss and morbidity observed in the pDC depleted and infected (“DT + infected”) mice was not simply a direct consequence of the increased bacterial load observed in these mice." (PMID 31024525, 2019). "Our results shows that this mechanism contributes to pDC unresponsiveness and likely blunt acute IFNα production during primary SIV infection, a mechanism probably transposable to human HIV-1 primary infection in which similar transient pDC deficiency was reported." (PMID 24497833, 2014). "A possible explanation is that pDC IFN production contributes to resistance to highly pathogenic influenza strains that might systemically spread from the lung early after infection, even if at low levels." (PMID 25400632, 2014). "Infection at delivery, on the other hand, was associated with loss of circulating pDC." (PMID 23239967, 2012). "Furthermore, these data suggest that pDC loss of function after infection may be associated with alterations in their cell-cell interactive properties and/or metabolic capacities which have not yet been described." (PMID 39920132, 2025). "Importantly, the pDC deficient mice showed higher infection load compared to the pDC intact mice." (PMID 24386207, 2013). "Altogether, our results identify a key role for LDHB in balancing pDC antiviral function and immunopathogenic potential during infection." (PMID 39920132, 2025). "In response to viral encounters and infection, pDC represents a unique subgroup of DC that releases type I interferon." (PMID 38536078, 2024). "Altogether, these results indicate that pDC sensing of infection in this model requires cognate interaction with MDMs." (PMID 37253946, 2023).
infection (continued). "The respective infection rate of different DC subsets was 1.97% ± 0.31, 1.71% ± 0.31, 1.54% ± 0.20, and 2.48% ± 0.15 for cDC, and 1.38% ± 0.23, 3.91% ± 0.62, 5.92% ± 0.71, and 5.74% ± 0.72 for pDC at 4, 12, 24, and 48 h post-infection." (PMID 36977141, 2023). "Another model is that an initial defect in pDC response can favor the infection of epithelial cells, which, in turn, can activate the macrophages." (PMID 36083891, 2022). "We establish the existence of a functional interaction (direct or indirect) between CD169+ MP and pDC in vivo that is needed to license pDC priming of type I IFN production in vivo during this infection." (PMID 36278864, 2022). "In this study, the PdR strain that lacked Erns RNase activity resulted in strong activation of pDC, and significantly stronger IFN-α production was observed when the pDC were stimulated by contact with infected MDM compared with direct infection." (PMID 35758667, 2022). "This rapid turnover of MHC-II complexes likely endows pDC with the capacity to continuously present new antigen at the site of infection, in contrast to cDC which provide superior antigenic memory." (PMID 36439124, 2022). "This is in line with a model where there is increased differentiation from pDC, through tDC, to cDC2 after infection." (PMID 34578420, 2021). "For example, infection with Alfort-187 led to a trend in the reduction in the frequency of both the cDC1 and pDC, while upon C-strain inoculation their frequency increased, significantly in the case of cDC1 cells." (PMID 34445493, 2021). "In fact, pDC have been described as the main source of systemic type I IFNs during infection of mice with several viruses including MCMV and HSV-2." (PMID 34843605, 2021). "In accordance with this, we saw a trend for elevated pDC numbers in tonsils isolated from C-strain inoculated pigs, compared to Alfort-187 infection." (PMID 34445493, 2021). "In particular, pDC depletion induced in Clec4c+/DTR mice significantly impaired the host immune response to MVA infection." (PMID 32765505, 2020). "There are several reported circumstances in which pDC function is altered or inhibited in response to infection, cytokines, or cross-linking of surface markers." (PMID 32023836, 2020). "To gain a better understanding of the inflammatory milieu and how it is affected by pDC depletion during C. rodentium infection, we investigated levels of cytokines in the serum using a cytometric bead array assay 10 days after infection." (PMID 31024525, 2019). "pDC were ablated by DT injection on the day before C. rodentium infection (day -1) and subsequently on days 1, 3, 5, 7, 9 after infection." (PMID 31024525, 2019). "We also observed a decrease in infected VeroE6 in the pDC/infected VeroE6 cocultures, suggesting that coculture with pDCs partially controlled VeroE6 infection by MOPV and LASV." (PMID 30901952, 2019). "It is possible that the pDC antiviral response controls infection once virus spreads systematically, as previously proposed in the context of Herpes Simplex virus infection." (PMID 29914621, 2018). "This new model also permitted the study of the possible cryptic pDC-mediated control of certain infections." (PMID 29914621, 2018). "Using RNA sequencing, longitudinal changes in pDC gene expression were examined in five adults before and at peak-infection." (PMID 28572564, 2017). "This suggests that splenic neutrophils are somehow primed by FL in a pDC-dependent manner for a rapid response to infection." (PMID 28228109, 2017). "Surprisingly, our recent report on early P. falciparum blood-stage infection found pDC to be minor contributors to the early IFN-α response." (PMID 28572564, 2017). "pDC significantly declined at peak parasitaemia and continued to fall 24 hours after antimalarial drug treatment in the 1,800 pRBC infection cohort (grey bars)." (PMID 28572564, 2017).
infection (continued). "The effect on neutrophil responses to infection, specifically, decreased neutrophil presence in wound-draining lymph nodes, was demonstrated 7 days after pDC depletion." (PMID 28228109, 2017). "While pDC gene expression was largely unchanged during early infection, a panel of eight genes significantly increased or decreased at peak-infection." (PMID 28572564, 2017). "Here we demonstrate pDC interacts with T cells in local draining nodes, it activate and differentiate T cells, guide them to infection sites." (PMID 29552679, 2017). "FL appears to increase the ability of the immune system to contain the infection locally in a pDC-dependent manner." (PMID 28228109, 2017). "In the present study, we demonstrated impaired pDC recruitment and decreased production of IFN-α, -γ, -λ in RAGE deficient mice during an early life PVM infection, resulting in a higher viral load in the airway epithelium." (PMID 28099113, 2017). "Again, only IFN-β appeared in detectable levels in the supernatants of lung homogenates of control (IgG) and anti-pDC treated mice, and appeared in reduced levels in pDC-depleted mice at weeks 2 and 8 of infection." (PMID 27992577, 2016). "A statistically significant decline in the antigen processing ability of CD11c+ cDC, CD11c− cDC, and CD4+ pDC was observed at 1 day post-infection, and this returned back to baseline levels by day 2 to 3 after infection." (PMID 27008425, 2016). "Further studies demonstrated a reduced expression of IDO mRNA in the lungs of pDC-depleted mice at all post-infection periods assayed." (PMID 27992577, 2016). "MHC class II, CD86 and CD40 expression on splenic pDCs remained unchanged during S. mansoni infection, indicating that the liver is a major site of pDC activation in this infection model." (PMID 26657145, 2016). "Following infection there was a greater relative percentage of pDC in both the blood and the spleen of the WT mice compared to the Ifnar1-/- mice." (PMID 26918359, 2016). "Later pDC responses probably result from direct virus contact in lymph nodes, as pDC activation returns to essentially normal levels by day 7 post infection in both mouse strains, when infectious virus has been cleared." (PMID 27405244, 2016). "At weeks 2 and 8 post-infection, an increased number of lung infiltrating leukocytes was detected in anti-pDC-treated mice." (PMID 27992577, 2016). "In the spleen an increase in the proportion of pDC was observed in the WT and this was abrogated in the Ifnar1-/- upon infection." (PMID 26918359, 2016). "pDC or intracellular TLR have been reported to be crucial for resistance to experimental infections with many viruses in mice but dispensable for resistance to natural infections in humans." (PMID 25954804, 2015). "pDC depletion prior to infection leads to a dramatic decrease of serum IFN-I levels but only to a modest and transient increase in viral loads in most organs." (PMID 25954804, 2015). "This emerging model for a cell-to-cell contact-dependent mechanism of pDC activation by infected cells argues for the existence of a localized pDC response at the site of infection." (PMID 26295405, 2015). "The frequency of PDC-a/immature pDC significantly decreased after infection as the pDC-b/HLA-DRlow late precursors and pDC–c/activated-matured populations increased." (PMID 24497833, 2014). "The pDC IFNα response increased as the duration of infection and, thus the replication levels, prior to co-culture increased." (PMID 25340500, 2014). "We investigated the contribution of pDC dynamics to both acute IFNα production and the rapid return of IFNα concentrations to pre-infection levels during acute-to-chronic transition." (PMID 24497833, 2014). "The production of MIP-1α/β by pDC was increased in the presence of HIV-1BaL infection and NAb 4E10 compared to HIV-1BaL alone." (PMID 25132382, 2014). "Depletion of pDC in in vivo infection models revealed that pDC contribute to virus clearance and constrain inflammation during infection." (PMID 24904586, 2014).